NLRP4 (NLR family pyrin domain containing 4)
Description:
May be involved in inflammation and recognition of cytosolic pathogen-associated molecular patterns (PAMPs) not intercepted by membrane-bound receptors. Acts as a negative regulator of the type I interferon signaling pathway by serving as an adapter to promote DTX4-mediated ubiquitination of activated TBK1, and its subsequent degradation. Suppresses NF-kappaB induction by the cytokines TNFA and IL1B, suggesting that it operates at a point of convergence in these two cytokine signaling pathways.
Synonyms: CT58; PAN2; PYPAF4; NALP4; RNH2; FLJ32126; CLR19.5
Tractability: PROTAC: ubiquitination databases record sites on it.
Gene: Protein-coding gene on chromosome 19 (55,836,540 to 55,881,855, forward strand). Ensembl gene ENSG00000160505.
Subcellular location (Human Protein Atlas): Mitochondria
Pathways (Reactome):
Immune System: IRF3 mediated activation of type 1 IFN; IRF3-mediated induction of type I IFN; Regulation of innate immune responses to cytosolic DNA
Gene Ontology:
Molecular function: molecular adaptor activity
Biological process: negative regulation of innate immune response; regulation of inflammatory response
Cellular component: cytoplasm; cytosol
Genetic constraint (gnomAD): Loss-of-function variants: 42 observed, 84.28 expected, observed/expected ratio (o/e) 0.5, 90% interval 0.39 to 0.64. The upper end of that interval is the gene's LOEUF score, 0.64, which puts it in group 2 of 6, group 1 being the genes least tolerant of losing a copy. Missense variants: 1,200 observed, 1,215.2 expected, observed/expected ratio (o/e) 0.99, 90% interval 0.94 to 1.04. Synonymous variants: 530 observed, 480.27 expected, observed/expected ratio (o/e) 1.1, 90% interval 1.03 to 1.19.
Homologues: Orthologues: chimpanzee NLRP4 (98% identical), macaque NLRP4 (92% identical), rat Nlrp4 (52% identical), pig NLRP4 (52% identical), rat Nlrp4a (51% identical), mouse Nlrp4c (50% identical), mouse Nlrp4e (50% identical), mouse Nlrp4a (49% identical), rat Nlrp4al1 (45% identical), rat Nlrp4f (44% identical), mouse Nlrp4f (44% identical), rat Nlrp4b (43% identical), and 1 more. Paralogues in human: NLRP9 (41% identical), NLRP12 (34% identical), NLRP3 (33% identical), NLRP14 (26% identical), NLRP13 (24% identical), NLRP2 (23% identical), NLRC5 (23% identical), NLRP7 (23% identical), NLRP5 (22% identical), NLRP1 (22% identical), NLRP11 (22% identical), NLRP8 (22% identical), and 8 more.
Diseases named in the same sentence as NLRP4 in open-access papers:
NLRP4 is named in the same sentence as 14 diseases in open-access papers, as found by Europe PMC text mining. Sharing a sentence is not in itself a finding about the gene and the disease. The quoted sentences say what the papers report.
viral infection (4 papers, 2017 to 2025). "Following virus infection, USP38 is recruited to the activated TBK1 by NLRP4 and removes K33-linked ubiquitin from K670, which enables K48-ubiquitination by DTX4 and TRIF." (PMID 33808506, 2021). "DTX4 is recruited by NLR Family Pyrin Domain Containing 4 (NLRP4) to mediate the proteasomal degradation of the Serine/threonine-protein kinase (TBK1), thereby restricting the induction of type 1 IFN following viral infection." (PMID 35204725, 2022). "DTX4 recruitment to TBK1 was shown to be dependent on the NOD protein family member NLRP4, which interacted specifically with activated (phosphorylated) TBK1 upon viral infection." (PMID 33808506, 2021). "NLRP4 can negatively regulate Tumor Necrosis Factor (TNF) and IL-1β-induced NF-κB activation, and can also negatively regulate type I interferon signaling in response to dsRNA, DNA, or viral infection, and regulate autophagy in response to bacterial infection." (PMID 41463370, 2025).
bladder cancer (1 paper, 2021). "However, NLRP3, NLRP4, and NLRP9 were significantly increased in the urine and tumor tissue samples of patients with bladder cancer compared with those in healthy people." (PMID 34869390, 2021).
CINCA syndrome (1 paper, 2023). Chronic Infantile Neurological, Cutaneous, and Articular (CINCA) syndrome is characterized by skin rash, joint involvement, chronic meningitis with granulocytes and, in some cases, sensorineural hearing loss and ocular signs. "Similarly, monocytes differentiated from CINCA syndrome patient-derived iPS cells with the NLRP4 mutation demonstrated excessive secretion of IL-1 and IL-18, and NLRC4 knockout in iPS cells led to notable reductions in pro-inflammatory cytokine secretion." (PMID 37876023, 2023).
colonic cancers (1 paper, 2021). "In this study, we analyzed mononucleotide repeats in coding sequences of NLRP1, NLRP2, NLRP4 and NLRP9, and found 1, 1, 1 and 8 frameshift mutation (s) in gastric (GC) and colonic cancers (CRC), respectively." (PMID 34257569, 2021).
liver cancer (1 paper, 2025). An epithelial or non-epithelial malignant neoplasm that arises from the liver. "To achieve this, we utilized siRNA transfection to knock down NLRP4 and NLRP5 in the liver cancer cell lines HCCLM3 and HepG2, and subsequently confirmed the knockdown efficiency through RT-qPCR analysis." (PMID 41050084, 2025).
lung carcinoma (1 paper, 2025). "NLRP4 could trigger a distinct anti-tumor ecosystem organized by TIGIT+TNFA+ NK and iNOS+ M1 in lung cancer, discovered in TCGA analysis and verified in murine model." (PMID 40087771, 2025).
pancreatic cancer (1 paper, 2024). "The results of this investigation show that the suppression of NLRP4 led to a greater susceptibility to olaparib in pancreatic cancer cell lines." (PMID 39187531, 2024). "Given that NLRP4 has been shown to stimulate autophagy and ROS production in pancreatic cancer cells, we conducted further investigations to explore the potential implications of these findings." (PMID 39187531, 2024). "Our findings revealed that NLRP4 upregulation contributes to increased resistance to olaparib in pancreatic cancer cells, both in vitro and in vivo." (PMID 39187531, 2024). "To assess this, we examined the formation of γ-H2AX foci in response to olaparib in various cell groups, including control cells, NLRP4-knockdown cells, NLRP4-overexpressing pancreatic cancer cells, and MitoQ-treated cells." (PMID 39187531, 2024). "The findings revealed no discernible disparity in intracellular ROS levels between NLRP4-knockdown pancreatic cancer cells and control cells treated with MitoQ." (PMID 39187531, 2024). "Intriguingly, the immunofluorescence assay revealed a reduction in the foci of BRCA1 and Rad51, two crucial proteins involved in DNA repair, in NLRP4-knockdown pancreatic cancer cells 6 h after olaparib removal." (PMID 39187531, 2024). "Intriguingly, an investigation was conducted on the γ-H2AX foci under various cellular conditions, including control, NLRP4 knockdown, NLRP4 overexpression in pancreatic cancer cells, and MitoQ treatment, after olaparib treatment." (PMID 39187531, 2024). "Specifically, NLRP4-generated mitochondrial ROS promote autophagy in pancreatic cancer cells upon exposure to olaparib." (PMID 39187531, 2024). "To assess the potential impact of NLRP4 on the resistance of pancreatic cancer cells to olaparib, we administered varying doses of olaparib to NLRP4-knockdown or control stable BxPC-3 (BRCA wild type) and Capan-1 (possessing BRCA2 mutation) cell lines." (PMID 39187531, 2024). "Our study provides evidence that NLRP4 induces intracellular ROS generation in pancreatic cancer cells, thereby promoting autophagy and contributing to olaparib resistance." (PMID 39187531, 2024). "To assess the effects of NLRP4 on tumor growth, olaparib sensitivity, DNA damage response, and autophagy in vivo, we conducted experiments using nude mice that were implanted with pancreatic cancer xenografts." (PMID 39187531, 2024). "Olaparib-induced apoptosis in pancreatic cancer cells decreased with NLRP4 complementation compared NLRP4 knockdown." (PMID 39187531, 2024). "Together, our research suggests that the upregulation of autophagy in pancreatic cancer cells plays a role in the development of resistance to olaparib, which is mediated by NLRP4." (PMID 39187531, 2024). "Additionally, the downregulation of NLRP4 expression hindered the growth of pancreatic cancer tumors in vivo." (PMID 39187531, 2024). "Moreover, the results obtained from MTS and colony formation assays demonstrated that the knockdown of NLRP4 significantly enhanced the inhibitory effect of olaparib on the proliferation of pancreatic cancer cells." (PMID 39187531, 2024). "Furthermore, the levels of intracellular ROS in NLRP4-knockdown pancreatic cancer cells and control cells treated with MitoQ remained unchanged, suggesting that NLRP4 triggers autophagy through ROS signaling." (PMID 39187531, 2024). "Indeed, our investigation revealed that the administration of olaparib resulted in a reduction in autophagy in NLRP4-knockdown pancreatic cancer cells, which was correlated with an increased sensitivity to olaparib." (PMID 39187531, 2024). "Moreover, the proliferation of pancreatic cancer cells and their resistance to olaparib were found to increase upon NLRP4 complementation when compared to the levels in cells with NLRP4 knockdown." (PMID 39187531, 2024). "Additionally, NLRP4 knockdown in pancreatic cancer cells led to a decrease in the half-maximal inhibitory concentration (IC50) values for olaparib." (PMID 39187531, 2024).
pancreatic cancer (continued). "The knockdown of NLRP4, the administration of MitoQ, and the use of the autophagy inhibitor CQ all contributed to the enhanced inhibitory effect of olaparib on the proliferation of pancreatic cancer cells." (PMID 39187531, 2024). "Notably, the comet tail distance of NLRP4-knockdown pancreatic cancer cells was significantly greater than that of the control group following a 24-h period of olaparib treatment." (PMID 39187531, 2024). "Taken together, our findings highlight the significant roles played by NLRP4 in the processes of autophagy and DNA repair when pancreatic cancer cells are treated with olaparib, thereby suggesting the potential therapeutic utility of olaparib in pancreatic cancer patients with low NLRP4 expression." (PMID 39187531, 2024). "In conclusion, this study demonstrated that NLRP4 enhances DNA repair capability and promotes ROS-induced autophagy under both basal conditions and treatment with olaparib, thereby leading to the development of olaparib resistance in pancreatic cancer cells both in vitro and in vivo." (PMID 39187531, 2024). "The findings of our research regarding the role of NLRP4 in regulating autophagy and olaparib sensitivity have revealed a distinctive function of NLRP4 in pancreatic cancer, which may have significant implications for determining the most effective treatment approach for pancreatic cancer patients." (PMID 39187531, 2024). "ChIP-qPCR experiments in pancreatic cancer cell lines confirmed significant H3K18ac enrichment in NOXO1 promoter region, which was diminished upon NLRP4 knockdown, suggesting NLRP4’s regulation of H3K18ac at the NOXO1 promoter." (PMID 39187531, 2024). "This study provides evidence that NLRP4, a constituent of the nucleotide-binding and oligomerization domain-like receptor (NLR) family, imparts resistance to olaparib in pancreatic cancer cells, both in vitro and in vivo." (PMID 39187531, 2024). "However, there was no discernible difference in autophagy levels between pancreatic cancer cells treated with MitoQ and those with NLRP4 knockdown, suggesting that NLRP4-induced autophagy is mediated by ROS production." (PMID 39187531, 2024).
Salmonella Infections (1 paper, 2022). Infections with bacteria of the genus SALMONELLA. "The pharmacological inhibition of PI3K or Akt, as well as the deletion of the rictor gene in B cells, is capable of rescuing the transcription of NLRP4 and IL-1β production, reflecting the control of Salmonella infection." (PMID 35805144, 2022).
infection (5 papers, 2016 to 2025). The state of being infected such as from the introduction of a foreign agent such as serum, vaccine, antigenic substance or organism. "After infection of T. gondii, mGbp2B (also named Gbp1) can activate inflammasome complex signaling cascades, which leads to Nlrp1, Nlrp3, Nlrp4, and pro-caspase-1 degradation resulting in converting the cell death type from pyroptosis to apoptosis." (PMID 32731337, 2020). "In canonical pathway, inflammasomes such as NLRP3, NLRP4 and AIM2 are responsible for recognizing extracellular pathogens infection and then activate the caspase-1, which cleaves GSDMD into the N-terminus and C-terminus fragments later." (PMID 35573789, 2022). "Moreover, the expression of NLRP1 and NLRP4 mRNA was not induced following infection with either strain of EIAV." (PMID 40522989, 2025). "Interestingly, T. gondii infection upregulated the expression of NLRC4, NLRP4, NLRP8, NLRP10, NLRP11, NLRP13, and NLRP14 mRNAs at both 4 and 8 h post-infection, but NLRP4, NLRP8, NLRP10, and NLRP11 mRNAs were significantly downregulated at 8 h post-infection compared to that at 4 h post-infection." (PMID 33712075, 2021).
tumor (3 papers, 2024 to 2025). "Furthermore, we assessed the impact of NLRP4 on the expression of tumor-associated proteins in xenografts using immunohistochemistry and western blot analysis." (PMID 39187531, 2024). "Compared with IFNγ, TNFA in NLRP4-OE tumor interstitial fluid (TIF) manifested consistent up-regulation regardless of CD8+ T cells deletion." (PMID 40087771, 2025). "In conclusion, PP2A-KD or LB-100 effectively recapitulate NLRP4’s anti-tumor effects, suggesting potential for clinical translation of NLRP4-eco." (PMID 40087771, 2025). "Utilizing bulk-RNA sequencing, proteomics, and mass spectrometry of mouse tumor tissues, we innovatively identified the downstream pathways of NLRP4 and verified them through co-immunoprecipitation (co-IP) and Western blot (WB) experiments." (PMID 40087771, 2025). "Altogether, we delineated NLRP4’s unexplored facets and discovered an NLRP4-driven anti-tumor ecosystem composed of TIGIT+TNFA+ NK and iNOS+ M1." (PMID 40087771, 2025). "Overall, we conclude that NLRP4 mediates an anti-tumor ecosystem in human tissues similar to that in mice." (PMID 40087771, 2025). "This study reveals a role of NLRP4 in shaping a distinct anti-tumor microenvironment, driven by NKomega (TIGIT+TNFA+ NK cells) and M1omega (iNOS+ M1 macrophages)." (PMID 40087771, 2025). "Using autologous PBMC-humanized NSG mice, we found that NSCLC tumor tissues with higher NLRP4 expression (NLRP4-high, determined by IHC) showed significant tumor suppression in vivo." (PMID 40087771, 2025). "It not only underpinned anti-tumor capabilities of NKomega and M1omega in NLRP4-eco, but also served as the communication bridge between them, which was independent of the well-established chemokines reprogramming effects." (PMID 40087771, 2025). "NLRP4-eco exerted tumor-suppression capacity through chemokine reprogramming including CCL5 and CXCL2." (PMID 40087771, 2025). "Although PD-L1 blockade (αPD-L1) could not further fuel the anti-tumor capacity of NLRP4, we confirmed an outstanding tumor-suppressive capacity of NLRP4-eco, which was far more intensive than αPD-L1 reprogrammed TIME (αPD-L1-eco)." (PMID 40087771, 2025). "Given PP2A’s broad regulatory role across various cell types, we first examined whether PP2A knockout in mice would impact NLRP4’s anti-tumor activity." (PMID 40087771, 2025). "Herein we demonstrated that NLRP4 overexpression (NLRP4-OE) served as the “key” to trigger a distinct anti-tumor ecosystem marked by the presence of TIGIT+TNFA+ NK cells and iNOS+ M1-polarised macrophages, a beneficial “lock” not reliant upon T cells (NLRP4-eco)." (PMID 40087771, 2025). "Notably, tumor cells were the exclusive source of overexpressed Ccl5 and Cxcl2, while Ccr5 + NK cells and Cxcr2 + macrophages were enriched in the NLRP4-OE TIME, a pattern that persisted throughout tumor progression." (PMID 40087771, 2025). "We next set out to dissect mechanisms behind NLRP4-OE anti-tumor capacity." (PMID 40087771, 2025). "To assess the functional relevance of these findings, we tested whether knockdown of CCL5 and CXCL2 in tumor cells (OE_shCCL5_shCXCL2) could abrogate the anti-tumor effects of NLRP4-OE." (PMID 40087771, 2025). "Furthermore, NLRP4-OE retained its phenotype in nude mice as well, thus demonstrating innate immune cells fully sufficient for mediating anti-tumor effects of NLRP4." (PMID 40087771, 2025). "We next tested whether in vivo inhibition of PP2A could recapitulate the anti-tumor effects of NLRP4." (PMID 40087771, 2025). "Finally, targeting PP2A by its inhibitor successfully mimicked the anti-tumor capacity of the overexpression of NLRP4." (PMID 40087771, 2025). "Besides, FK866, a selective NAMPT inhibitor, largely inhibited NLRP4-induced tumor cells apoptosis." (PMID 40087771, 2025).
tumor (continued). "In this study, we unveiled a novel role for NLRP4 within NSCLC TIME, acting as the catalyst to unlock an anti-tumor NLRP4-eco composed of NKomega and M1omega, much like identifying the driver mutation that underpins a particular cancer molecular subtype." (PMID 40087771, 2025). "In this study, TCGA datasets was used to confirm the prognosis value of the expression level of NLR family pyrin domain containing 4 (NLRP4) in NSCLC and the tumor tissues microarray was used to further check its clinical-relevance at protein-level." (PMID 40087771, 2025). "Except for NLRP4 and TRIM21, the expressions of the remaining 13 genes between normal and tumorous tissues differed significantly." (PMID 39185402, 2024). "Subsequently, a tumor cell line with stable NLRP4 overexpression was established and subcutaneous tumor models in C57BL/6J mice were used to validate the anti-tumor characteristics of NLRP4." (PMID 40087771, 2025). "Herein we have unveiled a hitherto obscure role of NLRP4, which orchestrated direct interaction with PPP2CA/B, subsequently triggering chemokine reprogramming through PI3K-Akt-NF-kB axis and thus curtailing tumor growth in a T-cells-independent manner." (PMID 40087771, 2025). "To verify whether NLRP4-eco was cancer-type conserved, we examined NLRP4-OE in MC38 cell-line, and confirmed the same anti-tumor capacity mediated by iNOS+ M1, TIGIT+TNFA+ NK and CD103+ DC, along with favorable OS, further emphasizing the unique landscape of NLRP4-eco across different cancer types." (PMID 40087771, 2025). "NLRP4-OE didn’t affect iNAMPT/eNAMPT levels in tumor cells, and neither macrophages nor NK could." (PMID 40087771, 2025). "Although no pronounced disparity was discerned between tumor and adjacent-tissue, a notable distinction was detected between stage III/IV specimens and corresponding adjacent-tissue, alluding to the distinctive clinical implications of NLRP4." (PMID 40087771, 2025).
bacterial infection (2 papers, 2013 to 2025). "NLRP4 further interacted with the class C vacuolar protein-sorting complex to inhibit phagolysosomal maturation, suggesting that NLRP4 and possibly other NLR family members play a role in autophagosome maturation following bacterial infection." (PMID 24367371, 2013).
cancer (2 papers, 2016 to 2025). A tumor composed of atypical neoplastic, often pleomorphic cells that invade other tissues. "NSCLC appeared to be the third most frequent cancer-type for NLRP4 genomic alterations, among which mutations (5.89%) were dominant." (PMID 40087771, 2025). "Genes such as MAGEA3 and MAGEA6 contributed targets for 7 cancer types each, while genes such as UMODL1, NLRP4, MAGEC2, ANKRD30A, and GPRC6A contributed targets for only 1 cancer type." (PMID 27439771, 2016).
NLRP4 also shares sentences with these, for which no sentence is quoted: Lewis lung carcinoma (1 paper); mastitis (1).